IL6 (interleukin 6)
Diseases named in the same sentence as IL6 in open-access papers (continued):
Sharing a sentence is not in itself a finding about the gene and the disease.
infection (continued). "Importantly, we have shown increased IL-6 expression in humans hospitalized with H1N1pdm infection, supported by prominent IL-6 responses in mouse models of severe H1N1pdm infection, heavily implicating IL-6 in the host response to H1N1pdm." (PMID 22679491, 2012). "IL-6 levels fluctuated but remained significantly elevated during the observation period and reached peak levels at day 6 post-infection, which was the time point when mice began to succumb to infection; these findings were consistent with the clinical symptoms observed." (PMID 22952892, 2012). "Infection has an important influence on cytokine production, particularly in the case of IL-6." (PMID 23176037, 2012). "IL-6 wild-type and IL-6−/− mice both exhibited severe illness following infection." (PMID 22679491, 2012). "However, nearly all (>99%) of the IL-6 and c-Jun mRNA was in the nuclear fraction following infection with rwt virus." (PMID 23028327, 2012). "While the IL-6−/− mouse model has repeatedly been used to identify unique functions of IL-6 in immune responses to infection, additional proinflammatory cytokines may drive inflammation in the absence of IL-6." (PMID 22679491, 2012). "Since soluble IL-6R (sIL-6Rα) could enhance rather than inhibit the biological activity of IL-6 both in vitro and in vivo, the elevated levels of sIL-6Rα detected in the first weeks of infection in BF patients might result in increased IL-6 activity." (PMID 21912565, 2012). "Our data suggests that variability in the induction of IL-6 may, at least, partially explain differences in the observed severity of human RSV disease associated with infection due to specific RSV genotypes." (PMID 22962966, 2012). "Both IL-6 and IL-8 were increased following infection of human PBMCs with CMV." (PMID 23061052, 2012). "Peritoneal macrophages stimulated with any of the three TLR agonists exhibited dramatically increased TNF and IL-6 levels at one, three and five days after infection with P. yoelii 17XNL or 17XL, which was consistent with the response of macrophages to pRBC lysate." (PMID 22463100, 2012). "Our findings are that miR-H6 mimics could inhibit HSV-1 productive infection in HCE cells as well as accompanied IL-6 release." (PMID 22550533, 2012). "The data suggest that account should be taken of infection in patients where inflammatory markers are being evaluated and that IL-6 may be a valuable early indicator of CSF infection in patients with EVDs." (PMID 23176037, 2012). "We evaluated TLR2/1L-induced innate immune cytokines e.g. TNF-α, IL-1β, IL-6, IL-23 and IL-12, known to be critical players in the control of Mtb infection, and chemokines such as Gro-α and IL-8 that are required for cell recruitment to the site of infection." (PMID 22866178, 2012). "Interestingly, attenuation of IL-6 after 405 nm treatment was only evident if 405 nm irradiation was applied promptly after infection; the effect was lost if applied 24 h post-infection." (PMID 22894815, 2012). "Induction of IL-6 seemed particularly sensitive to infection in the patients studied and these data suggest that monitoring IL-6 might be used as a marker of infection." (PMID 23176037, 2012). "During severe infection, uncontrolled release of cytokines such as tumor necrosis factor-alpha (TNF-α) and interleukin-6 (IL-6) may cause a so-called cytokine storm." (PMID 21931850, 2011). "However, in the mice fed continuously with the probiotic (Lc-S-Lc group), the IL-6 release into the intestinal lumen remained stable 7 and 10 days post-infection." (PMID 21813005, 2011). "The authors hypothesized that over-production of IL-6 in wt mice would be detrimental to the outcome of PTV infection, pointing out that the balance of cytokines might alter the pathogenesis of PTV." (PMID 21666766, 2011).
infection (continued). "As expected, infection of pig-tailed macaques with PBj-wt virus led to development of the characteristic acute enteropathic disease, accompanied by T cell activation as well as elevated IL-2 and IL-6 serum levels." (PMID 21366921, 2011). "However, over the next 7 days nearly a third of the IL-6 -/- mice succumbed to infection (*P = 0.0473, Logrank Test)." (PMID 21966268, 2011). "This suggests that the higher intraperitoneal levels of IL-6 early after K. pneumoniae infection may contribute to enhanced bacterial clearance and higher likelihood of surviving infection." (PMID 22110673, 2011). "However, we found that in both SHIV162p3 and SIVmac251 infected macaques, both Th-1 (IL-2, IFN-γ) and Th-2 (IL-4, IL-5, IL-6, IL-10, and IL-13) type cytokines were markedly elevated after infection." (PMID 21464951, 2011). "Moreover, we indicated nDens of 2 genes induced and 2 genes repressed in all infection performed and nDens of all genes discussed above (IL-1β, IL-6, IL-12, TNF-α, IL-10, ADAM19, CCR7, CCL20 and IL-18)." (PMID 21436989, 2011). "On day 9 post infection, Pigeon04 induced mRNA expressions of IL1β and IL6 in 1 lung sample." (PMID 21826229, 2011). "Interestingly, IL-8 was significantly upregulated at 96 hpi with RSV A2 and BT4a, while IL-6 was significantly increased only following infection with the latter virus." (PMID 21272337, 2011). "However, to our surprise, we found that upon infection with T. gondii, except for impaired IL-12p40 production, 3d mice showed high levels of IL-6, MCP-1, IFNγ, and TNFα in their sera." (PMID 20865117, 2010). "In comparison to C57Bl/6 mice, Balb/c had delayed IFN-γ and IL-6 response, an early IL-10 that persisted to day 15 and increased by day 28 post-infection, and IL-5 levels that were significantly elevated by day 15 and remained so at day 28 post-infection." (PMID 20625554, 2010). "Serum MIF peaked 9 h post-infection and then declined; IL-6 and TNF-α continuously increased." (PMID 20939898, 2010). "• LBP, IL-6 and CRP levels are associated with the severity of infection in children population." (PMID 20158885, 2010). "In addition, serum IL-6 levels and IL-10 levels were significantly increased in the subgroup with subsequent infection and confirmed within this cohort (data not shown)." (PMID 20090932, 2010). "Higher levels of IL-6 and IL-8 early in course of infection may be prognostic markers for progression to DHF and seem to play a role in the disease pathogenesis." (PMID 20090849, 2010). "While IL-1β plays an important role in the inflammatory response against infection by increasing the expression of endothelial adhesion factors, thus allowing infiltration of leukocytes at the site of infection, IL-6 is a proinflammatory cytokine released in response to trauma or tissue damage." (PMID 22069560, 2010). "TLR activation upregulates transcription of proinflammatory cytokines interleukin-1β (IL-1β), tumor necrosis factor alpha (TNFα), and interleukin-6 (IL-6), which are essential for the recruitment of immune cells to the site of infection and controlling Mtb infection." (PMID 20808838, 2010). "However, IPS-1−/− cells do secrete some IL-6 following infection with RABV, and thus, the use of IPS-1 independent pathways to induce NF-κB activation, in contrast to type I IFN activation, seems to be utilized." (PMID 20661430, 2010). "By day 2 of infection, significant fold increases above background in the mean levels of IL-6 (40–55-fold), IL-17 (9–14-fold), KC (8–11-fold), MCP-1 (10–14-fold), and RANTES (2–4-fold) were observed in lung homogenates from all vaccinated groups, but not unvaccinated control mice." (PMID 20967278, 2010). "BMSC response to neurotrophins, including the up-regulation of IL-6, may alter their support of hematopoiesis and regulate the availability of inflammatory cells for migration to sites of injury or infection." (PMID 20300619, 2010).
infection (continued). "Interestingly, patients receiving cardiac surgery exhibited markedly higher levels of IL-6 following the procedure in all studied genotypes as compared with patients suffering from infection approximately 24 hours following the insult." (PMID 20525286, 2010). "IEC react on bacterial as well as immune-derived pro-inflammatory signals by secreting cytokines and chemokines like interleukin 6 (IL-6) and interferon γ-induced protein 10 (IP-10) to activate and attract Th1-immune cells and phagocytic cells to the site of infection." (PMID 19197385, 2009). "Furthermore, we detected increased levels of IL-6 in the serum of infected P58IPK−/− mice at day 5 post infection." (PMID 19461876, 2009). "Similarly, the secretion of IL-6 was also increased following infection with the lysX mutant compared to the wild type and complemented strains." (PMID 19649276, 2009). "This suggests that MCP-1 is regulated by IL-6 following CB3 infection." (PMID 19587788, 2009). "Similarly, the cytokines Il1α, Il5, Il6, and Il12 were secreted into the broncho-alveolar space of both strains after infection but were higher in DBA/2J mice." (PMID 19293935, 2009). "The levels of TNF-α, IL-1β and IL-6 in BAL before infection were similar in both groups." (PMID 19835595, 2009). "In patients with AP, low HLA-DR expression and high IL-6 concentration could predict severity and infection in samples taken shortly after admission." (PMID 19442309, 2009). "The differences between influenza H5N1 and H1N1 viruses achieved statistical significance with IFN β following apical (p < 0.05) and basolateral (p < 0.01) infection, IL-6 following apical infection (p < 0.01), and IP-10 following basolateral infection (p < 0.05)." (PMID 19874627, 2009). "Based on the confirmed roles of IL-6, a high-level expression of IL-6 at the early stage (one day post-infection) may be induced by the body’s stress response secondary to acute infection." (PMID 19590756, 2009). "Therefore, lack of IL-6 results in greater chronic disease severity post-infection and is indicative of a regulatory role for IL-6 in the host response to infection and the ensuing chronic pathology." (PMID 19587788, 2009). "• Low HLA-DR expression and high IL-6 concentration could predict severity and infection in samples taken shortly after admission." (PMID 19442309, 2009). "Increased expression of IL-6 at the late stage (seven days post-infection) may play a role in stimulating lymphocyte activation, proliferation, and differentiation, and it may be important in promoting the humoral and cellular immune responses." (PMID 19590756, 2009). "By contrast, G-CSF, TNF, and MCP-1 levels in the kidneys at 24 and 48 h showed associations with lesion parameters at both times, possibly indicating involvement of these effectors in the progression of infection subsequent to the neutrophil-recruiting early activities of KC, IL-6 and MIP-1β." (PMID 19641609, 2009). "IL-6 is critical in the host defense of the cornea during infection with Pseudomonas aeruginosa." (PMID 19590756, 2009). "These experiments reveal a critical role for IL-6 in ensuring, within the timeframe of an acute infection with a cytopathic virus, that antigen-specific Tregs have no opportunity to down-modulate the immune response, thereby favoring pathogen clearance and survival of the host." (PMID 18389078, 2008). "IL-6, in addition to its pro-inflammatory role, is considered to be a cytokine of importance for the development of an antigen-specific humoral response during some infections." (PMID 18700003, 2008). "Cancer patients undergoing treatment with systemic cancer chemotherapy drugs often experience debilitating fatigue similar to sickness behavior, a normal response to infection or tissue damage caused by the production of the inflammatory cytokines IL-1β, TNF-α, and IL-6." (PMID 18523641, 2008). "IL-6 isproduced by a variety of cell types during infection, trauma, and immunologicalchallenge." (PMID 18604304, 2008).
infection (continued). "Our novel findings provide direct empirical evidence in humans for involvement of the dopamine system in behavioral consequences of peripheral inflammation, highlighting a role for IL-6 and substantia nigra neural activity in infection-related psychomotor impairments." (PMID 18242584, 2008). "IL-6 has a wide range of biological activities, among them proinflammatory properties and a role as the main stimulus for acute phase protein synthesis and release from liver in infection." (PMID 18226201, 2008). "Since IL-6 production was prominent during the acute phase of infection and within the timeframe of virus specific T cell activation we considered it reasonable to hypothesize that IL-6 plays a role in shaping the T cell response to influenza virus." (PMID 18389078, 2008). "Moreover, since LLO− mutant bacteria stimulated robust but temporally limited JNK phosphorylation and little IL-6 secretion, we infer that prolonged JNK activation is necessary for maximal IL-6 production during intracellular infection by L. monocytogenes." (PMID 18769721, 2008). "Comparable neutralizing antibody activity was observed in WT and IL-6−/− serum analyzed 8 weeks post infection thus the impairment in the CD4+ T cell memory response observed in the IL-6−/− mice did not impinge on their ability to generate adequate neutralizing antibodies." (PMID 18389078, 2008). "Thelevels of TNFα and IL-6 as found in the presentstudy in daytime dialysate are on the whole comparable to those described in several studies in CAPD patients withstandard glucose dialysis solutions during an infection-free period." (PMID 18274646, 2007). "In order to study the extent and kinetics of the inflammatory response, we sacrificed WT, TLR2 KO, and TLR4 KO mice at multiple time points after infection and measured the concentrations of the proinflammatory cytokines TNFα and IL6 and the anti-inflammatory cytokine IL10 in lung homogenates." (PMID 17676990, 2007). "However, when the data were analyzed using multivariate logistic regression, CRP on the second day and again CRP and IL-6 on the fifth day were the only predictive factors for postoperative infection." (PMID 17505683, 2007). "Previous studies have shown IL-6 tobe a useful marker of early infection in the newborn." (PMID 18274637, 2007). "IL-6 levels in patients with infection were significantly higher (p = 0.01) both on the second postoperative day (OR = 6.91; 95% CI: 1.06-45.22; p = 0.04) and on the fifth postoperative day (OR = 14.64; 95% CI: 1.90-113.04; p = 0.01), even when LOS entered as a covariable." (PMID 17505683, 2007). "Pro-inflammatory cytokines such as IL-1β, IL-4, IL-6 and IL-7 participate in this infection." (PMID 17935610, 2007). "Cpn infection of vascular smooth muscle cells increases interleukin-6 (IL-6) secretion in vitro." (PMID 18062811, 2007). "IL-6, CRP and LBP appear to be of equal value as diagnostic infection markers in our study." (PMID 16569262, 2006). "Also, association parameters including oxygen saturation, PaO2/FiO2, respiratory index, interleukin 6 value, or age above 60 could improve the prediction of these scores in order to assess the infection severity." (PMID 41562685, 2026). "Administering additional IL-6 or JAK inhibitors after patients have entered CARS may exacerbate immunoparalysis and increase the secondary infection risk, whereas the premature delivery of rIL-7 or GM-CSF during the cytokine storm peak can theoretically fuel hyperinflammation." (PMID 41521316, 2026). "The classic signaling pathway mediates protective immune functions upon the binding of IL-6 to the membrane-bound IL-6 receptor (IL-6R) and the gp130 coreceptor, thereby recruiting and activating immune cells and promoting pathogen clearance, which are crucial for host defense against infection." (PMID 41521316, 2026).
infection (continued). "Once activated, these cells secrete proinflammatory cytokines, including TNF-α, IL-6, IL-1β, and IL-12 in proportions that vary according to fungal morphology, promoting an environment that favors the differentiation of Th1 and Th17 lymphocytes in the early stages of infection." (PMID 41590416, 2025). "In patients with CSKP infection, the levels of CRP, PCT, and IL-6 in the death group were significantly higher than those in the survival group (p < 0.05), indicating that the values of these three indicators are positively correlated with the severity of the infection." (PMID 39975685, 2025). "Potential exclusion criteria of future clinical trials may be derived from the known clinical side effect profile of IL-6 inhibitors, e.g., patients with certain infections, active tuberculosis or malignancies, abnormal blood cell counts, and high risk of gastrointestinal perforation." (PMID 39857830, 2025). "Infection with the highly contagious SARS-CoV-2 virus, the causative agent behind the coronavirus 2019 (COVID-19) pandemic, has been associated with an increase in circulating tumour-necrosis factor (TNF) and IL-6, in part contributing to hypercoagulation and platelet dysfunction." (PMID 40497942, 2025). "IL-6 is also closely linked with physiological aging, irrespective of active infection." (PMID 40333142, 2025). "Additionally, the infection induced upregulation of the pro-inflammatory cytokines such as interleukin-1beta (IL-1β) and interleukin-6 (IL-6), and downregulation of the anti-inflammatory cytokines such as interleukin-10 (IL-10) and transforming growth factor beta (TGF-β)." (PMID 40571943, 2025). "IL-6 becomes detectable within 1 h after triggering an infectious stimulus, reaches its plateau in 4 to 6 h, and the IL-6 release may be essentially abolished by 36 h, even while the infection remains unchallenged; as IL-6 blood level drops, acute phase reactants (such as CRP) increase." (PMID 40171168, 2025). "We previously reported that the amniotic fluid NGAL level was a useful predictive factor for FIRS, which is related to infection; its predictive ability was equivalent to that of interleukin-6 and might reflect both maternal and fetal inflammatory conditions and their impact on fetal status." (PMID 41567428, 2025). "Similarly, IL6 is released in response to inflammation, infection, and injury." (PMID 40420945, 2025). "However, the major model component IL-6, the main driver of T cell depletion throughout the infection, mimics the effects of other cytokines and drugs that inhibit T cell recruitment, suggesting our results can be extended to other anti-inflammatory cytokines not included in our model." (PMID 40489562, 2025). "IL-6 enhances the ability of HPV-infected cells to evade T-cell immune responses, and at high concentrations, may be crucial for the persistence of high-risk HPV (HR-HPV) infection and disease progression." (PMID 40008312, 2025). "However, tissues for IL-6 and IL-8 measurements were sampled 9 (±1) days after infection, which may be too late to detect acute inflammation." (PMID 40061905, 2025). "PCI surgical trauma, ischemia–reperfusion injury, or postoperative infection can activate the immune system, leading to the massive release of inflammatory cells such as neutrophils and monocytes, and promoting the elevation of pro-inflammatory cytokines (such as IL-6 and TNF-α)." (PMID 40564453, 2025). "PD-1 can reduce levels of inflammatory cytokines, including TNFα, IL-1β, IL-6, and iNOS, suggesting that an increase in eosinophil numbers may act to reduce inflammation and tissue damage induced by catheterization and infection, consistent with our observations here of eotaxin effects during CAUTI." (PMID 40980878, 2025). "Therefore, the levels of IL-6 and IL-1β are higher during infection and inflammation." (PMID 39858184, 2025).